LPCAT1 (lysophosphatidylcholine acyltransferase 1)
Diseases named in the same sentence as LPCAT1 in open-access papers (continued):
Sharing a sentence is not in itself a finding about the gene and the disease.
tumor (continued). "Several metabolic mechanisms have been reported to be involved in tumor metastasis, but the characterization of the mechanisms regulated by LPCAT1 in ESCC cells is limited." (PMID 34518524, 2021). "LpCat1 was generally recognized as an oncogene due to its up-regulation in a variety of tumor tissues including HCC." (PMID 34178664, 2021). "Lysophosphatidylcholine acyltransferase 1 (LPCAT1) plays a key role in the lipid remodelling and is correlated with various neoplasms." (PMID 34419067, 2021). "Compared with the control group, the tumor volume and weight of the LpCat1 overexpression group significantly increased." (PMID 34178664, 2021). "Then, we found that LPCAT1 was highly expressed in tumour samples compared with that in normal tissues, and lower survival rates were observed in the groups with high LPCAT1 expression." (PMID 34016103, 2021). "Overexpression of LPCAT1 in ESCC potentiates multiple tumor characteristics, including cell migration and invasion." (PMID 34518524, 2021). "The scores were compared between the high-expression group and low-expression group and the results revealed that only LPCAT1 was related to the tumour microenvironment." (PMID 34016103, 2021). "The tumor growth was substantially inhibited in the LpCat1 depletion group, as shown by smaller tumor size and lighter tumor weight." (PMID 34178664, 2021). "We also observed that the expression of SREBP-1 in the nucleus of tumor tissues with high LPCAT1 expression is significantly higher than that in the nucleus of tumor tissues with low LPCAT1 expression." (PMID 34518524, 2021). "LPCAT1 overexpression in CRPC cells drives tumor progression via increased mRNA synthesis and PAF production." (PMID 33137125, 2020). "Prior to paclitaxel dosing, LPCAT1 led to little increase in tumor growth, whereas upon paclitaxel treatment growth was more completely suppressed in control tumors than in LPCAT1 overexpressing tumors." (PMID 33137125, 2020). "This experiment demonstrated increased tumor growth in cells expressed elevated levels of LPCAT1 (p < 0.05)." (PMID 33137125, 2020). "This was consistent with differences in tumor weight, and suggests that LPCAT1 renders CRPC cells resistant to paclitaxel therapy in vivo." (PMID 33137125, 2020). "To extend these findings to a more physiologically relevant setting, we conducted a xenograft tumor experiment to assess LPCAT1-dependent tumor growth." (PMID 33137125, 2020). "Together, these results showed that blockade of LPCAT1 activation suppressed tumor growth and brain metastasis of NSCLC cells in vivo." (PMID 30791942, 2019). "The result indicated that tumor growth was substantially inhibited in LPCAT1 depletion group, as shown by smaller tumor size and lighter tumor weight." (PMID 30791942, 2019). "shRNA-mediated depletion of LPCAT1 not only abrogated cell proliferation, migration and invasion in vitro, but also arrested tumor growth and brain metastases in vivo." (PMID 30791942, 2019). "According to our study, expression levels of LPCAT1 were strongly associated with amplifications of HER2 and MYC, negative ER and PR status and PTEN deletions, which are all linked to adverse tumor features and poor patient outcome." (PMID 31533087, 2019). "Consistent with tumor growth inhibition, the result showed that in tumors with depleted LPCAT1 the expression of PCNA, CD34 and MMP9 were diminished (P < 0.05)." (PMID 30791942, 2019). "Kaplan-Meier survival curves showed that the high expression of LPCAT1 in tumours correlated with worse survival in ccRCC patients (log-rank test, p = 0.018)." (PMID 28494778, 2017). "Additionally, data indicate that LPCAT1 expression levels were generally higher in patients in the immunotherapy response group across multiple immunotherapy cohorts in the Tumor Immune Dysfunction and Exclusion (TIDE) dataset." (PMID 40723289, 2025). "LPCAT1 mRNA and protein levels were significantly elevated in tumor than normal tissues." (PMID 39781455, 2025).
tumor (continued). "The IHC assay also revealed a significant increase in LPCAT1 expression in tumor tissues." (PMID 39781455, 2025). "Furthermore, gene coexpression analysis was conducted to explore the relationships between GSTP1 and LPCAT1 expression and the tumor microenvironment (TME) and between GSTP1 and 33 immune-related genes in tumors in the TCGA database." (PMID 40555906, 2025). "Given that ccRCC is characterized as a “metabolism-related disease,” particularly in terms of lipid metabolism, the unexplored HIF-2α/LPCAT1/ACLY pathway may present a promising therapeutic target for controlling this tumor." (PMID 39781455, 2025). "The positive rate of LPCAT1 in tumor tissues is significantly higher than in normal tissues." (PMID 39781455, 2025). "All our findings together illustrated that LPCAT1 functions as a regulator in tumor-infiltration of immune cells in HCC, and targeting LPCAT1 may improve the efficacy of immunotherapy in HCC." (PMID 36307879, 2022). "There have been several studies on the mechanism of LPCAT1 in tumor cells." (PMID 36307879, 2022). "Zhang found that LPCAT1 expression was related to tumor grade, ECOG score, AFP and TNM stage." (PMID 36307879, 2022). "Finally, an in vivo study was performed to observe the effect of LPCAT1 knockout in PC-9R cell tumor-bearing mice." (PMID 35399731, 2022). "We established mouse xenograft tumor models to investigate whether elevated LPCAT1 expression affects tumor growthin vivo." (PMID 35880567, 2022). "In addition, through RNA-sequencing and western blot analysis, we observe that the TGF-β/Smad2/3 signaling pathway is of great importance in the tumor-promoting function of LPCAT1." (PMID 35880567, 2022). "There is increasing evidence that the expression of LPCAT1 is overexpressed in multiple human tumors and may be involved in tumor proliferation and metastasis." (PMID 36307879, 2022). "Collectively, high level of LpCat1 promoted tumor progression, which might be a potential therapeutic target for HCC." (PMID 34178664, 2021). "Collectively, such findings indicate the vital roles LPCAT1 play in tumour onset and progression." (PMID 34419067, 2021). "Also, LPCAT1 expression shows an ascending pattern in male, age < 60, and microvascular tumour thrombus HCC patients." (PMID 34419067, 2021). "Additionally, the expression level of LPCAT1 in tumour tissues was also significantly higher than that in paired normal tissues." (PMID 34016103, 2021). "Based on its molecular function as a key enzyme of lipid synthesis in the Land’s cycle, it is believed that LPCAT1 upregulation reflects the increased demand for lipid-depending cellular structures such as membranes and fatty acids in rapidly proliferating tumor cells." (PMID 34148155, 2021). "Only LPCAT1 was significantly correlated with the tumour microenvironment." (PMID 34016103, 2021). "Moreover, we proved for the first time that LpCat1 directly interacted with STAT1 which was generally recognized as a tumor suppressor in HCC." (PMID 34178664, 2021). "Therefore, further studies should be conducted to verify the accuracy of the combined analysis of LPCAT1 expression, GPLs and the amounts of tumour-infiltrating immune cells in UCEC patients." (PMID 34016103, 2021). "In order to examine the effect of LpCat1 on tumor metastasis in vivo, we established metastasis model by implantation of lentivirus-mediated stably transfected Hep3B cells with up- or down-regulation of LpCat1 expression by tail vein injection." (PMID 34178664, 2021). "Anoikis resistance is the first step toward tumor metastases but whether LPCAT1 affects anoikis in ESCC cells was unknown." (PMID 34518524, 2021). "The frequency of LPCAT1 positivity depended on the histological tumor type." (PMID 31533087, 2019). "LPCAT1 expression was evaluated in tumor tissues from LUAD patients and LUAD cell lines." (PMID 30791942, 2019).
tumor (continued). "Apart from the need of producing lipids for dividing cells, LPCAT1 expression could also impact tumor cell proliferation by the production of metabolic intermediates for synthesis of cellular signaling molecules." (PMID 31533087, 2019). "Since tumor cell metastasis is an important part of tumor progression, we raised a question whether LPCAT1 is involved in the metastasis of NSCLC cells." (PMID 30791942, 2019). "Moreover, LPCAT1 expression levels were positively correlated with tumor differentiation and negatively with lymph node metastasis, tumor stage and tumor depth, assuming a potential prognostic value." (PMID 27916803, 2016). "The LPCAT1 expression level could differentiate between prostate cancer subtypes, and could correlate with the Gleason score and tumor staging systems, as principal prognostic index." (PMID 27916803, 2016). "Therefore, it is important to investigate whether LPCAT1 regulates fatty acid metabolism in ccRCC, as well as the mechanisms that influence tumor formation." (PMID 39781455, 2025). "For instance, modulating lipid metabolic pathways with existing inhibitors targeting LPCAT1 or ACSL4 may disrupt aberrant lipid flux within tumor cells, impeding tumor growth and overcoming chemoresistance, while LCAT inhibitors could impair membrane integrity and energy homeostasis in HCC cells." (PMID 40500772, 2025). "Besides, LPCAT1 may play its tumorigenic role by enhancing tumor immune cell infiltration and immune checkpoint expression." (PMID 35615532, 2022). "It is possible that TERT upregulation might be an early event in ETT and that LPCAT1-TERT fusion might represent a later event capable of driving disease aggressiveness as has been observed for alternative TERT promoting events in tumor types where an LPCAT1-TERT fusion has been reported." (PMID 34033669, 2021). "In addition, the xenograft model was established to evaluate the effect of LpCat1 on tumor growth." (PMID 34178664, 2021). "Based on its molecular function as a key enzyme of lipid synthesis in the Land’s cycle it is believed that LPCAT1 up-regulation reflects a consequence of the increased demand for lipid-depending cellular structures such as membranes and fatty acids in rapidly proliferating tumor cells." (PMID 31533087, 2019). "Our data further demonstrate that LPCAT1 regulates the expression of COX17, suggesting that the promotion of Cytochrome c oxidase activity and tumor bioenergetics by LPCAT1 is mediated through COX17." (PMID 41792107, 2026). "In GSE25097 dataset, compared with normal tissues, the expressions of CDC20, LPCAT1, and SPP1 were significantly upregulated, while PON1 was significantly downregulated in tumor tissues, which was consistent with the results in TCGA." (PMID 40404896, 2025). "Increased CDC20, LPCAT1, and SPP1 and reduced PON1 were found in tumor tissues than normal tissues, as well as in advanced patients than early-stage patients." (PMID 40404896, 2025). "Specifically, we identified that LPCAT1 serves as a key mediator connecting SOX2 transcriptional regulation with cholesterol biosynthesis, thereby creating a vicious cycle that promotes tumor aggressiveness." (PMID 41358198, 2025). "Studies have shown that LPCAT1 is upregulated in HCC cells, potentially enhancing the invasive and migratory capabilities of tumor cells." (PMID 40835789, 2025). "The results of TCGA-LIHC dataset analysis showed that compared with normal tissues, CDC20, LPCAT1, and SPP1 were significantly up-regulated and PON1 was significantly down-regulated in tumor tissues." (PMID 40404896, 2025). "The role of LPCAT1 in tumor immunity warranted further in-depth study; so, we further explored the correlation between the expression of immune cell biomarkers in LIHC and LPCAT1." (PMID 35615532, 2022). "LPCAT1, as a key member of the LPCAT family, has been demonstrated to play an important role in different tumor types." (PMID 35880567, 2022).
tumor (continued). "Our findings also revealed significant correlations between KPNA2, LPCAT1, KIF2C, and SPP2 expression and three clinical traits, including ECOG (p < 0.01), vascular tumour cell type (p < 0.05), and tumour status (p < 0.05)." (PMID 35915607, 2022). "Literature review identified only three previous reports of LPCAT1-TERT fusions, each identified in distinct neoplasms affecting neurological, liver, and lung tissue respectively." (PMID 34033669, 2021). "Specifically, increased LPC acyltransferase (LPCAT1, LPCAT2) activities in neoplastic tissues have been proposed to confer tumor resistance through elevated PC production." (PMID 32733643, 2020). "The results showed LPCAT1 expression in ccRCC was significantly correlated with unfavourable pathological features (higher tumour grade, higher TNM stage and larger tumour size) and clinical outcomes." (PMID 28494778, 2017). "LPCAT1 and ATX were highly expressed in tumor tissues and FAE significantly decreased the expression of these two enzymes." (PMID 27991567, 2016). "While LPCAT1, AIFM2, and VCP have not been directly validated as diagnostic biomarkers, they are functionally implicated in tumor pathogenesis." (PMID 40804485, 2025). "This suggested that high expression of CDC20, LPCAT1, and SPP1, as well as low expression of PON1, may affect the immune escape and cell metabolism of tumor cells, reducing TACE treatment sensitivity." (PMID 40404896, 2025). "By coordinating the localization of the HBO1/KDM9 complex, Linc01711 specifies the histone modification pattern on target genes, such as lysophosphatidylcholine acyltransferase 1 (LPCAT1), thereby facilitating cholesterol synthesis and contributing to tumor progression." (PMID 40722703, 2025). "Furthermore, we confirmed the ability of major members of this gene family to participate in tumor cell proliferation, migration, and invasion by silencing AGPAT5, LCLAT1, and LPCAT1, respectively, in HepG2 cell lines." (PMID 36845084, 2023). "Moreover, we detected the expression of LpCat1, STAT1, CyclinD1, ki67 and MMP-9 in the tumor tissues by immunohistochemistry." (PMID 34178664, 2021). "Interestingly, overexpression of LPCAT1 gene was shown in CRC, although all other members of the metabolic pathway were downregulated in tumours matched to NCT." (PMID 31949199, 2020). "In this study, LPCAT1 immunostaining was found to be higher in tumor tissue than in non-neoplastic epithelial breast tissue." (PMID 31533087, 2019). "The mRNA and protein levels of LPCAT1 were up-regulated in ccRCC tissues compared with normal renal tissues, and LPCAT1 expression was significantly correlated with unfavourable pathological features (higher tumour grade, higher TNM stage and larger tumour size) and overall survival." (PMID 28494778, 2017). "LPCAT1 showed upregulated expression in 3715 HCC specimens as opposed to 3105 non-tumour specimens." (PMID 34419067, 2021). "Increased LPCAT1 expression patterns varied from gender (male: 3.28 ± 3.10 vs. female: 1.73 ± 1.66; P = 0.001), age (< 60: 3.33 ± 3.22 vs. ≥ 60: 2.17 ± 1.65; P = 0.002) and microvascular tumour thrombus (with thrombus: 3.50 ± 3.20 vs. without thrombus: 2.64 ± 2.71; P = 0.040)." (PMID 34419067, 2021). "LPCAT1-TERT fusions were confirmed absent from all internal and public normal and tumor tissue databases profiled." (PMID 34033669, 2021). "In this study, we investigated the differences in gene expression between normal tissues and tumor tissues, as well as TACE response and non-response groups, and intersected them with MRGs, successfully identifying four key genes (CDC20, LPCAT1, PON1, and SPP1)." (PMID 40404896, 2025).
infection (4 papers, 2022 to 2025). The state of being infected such as from the introduction of a foreign agent such as serum, vaccine, antigenic substance or organism. "In the infection group, the expression of Alox5 and Cox-2 was upregulated significantly, and the regulatory enzymes Lpcat1 and Lpcat2, which are involved in PC remodeling, were also significantly upregulated." (PMID 40463366, 2025). "Regulatory enzymes related to phospholipid remodeling, namely, Lpcat1, Lpcat2, and Mboat1, are also upregulated upon infection." (PMID 40463366, 2025). "After verification of the interference efficiency of si-RNA, si-LPCAT1 and si-Ctrl Ishikawa cells were harvested after three days of infection for the subsequent assays." (PMID 35880567, 2022). "Furthermore, the altered PC/LPC and PE/LPE ratios, which correlated with pro-inflammatory cytokines, CRP levels, and disease severity, suggest that lipid remodeling enzymes such as lysophosphatidylcholine acyltransferase 1/2 (LPCAT1/2) are tightly regulated in infection-induced stress responses." (PMID 41011521, 2025). "Additionally, the expression of Lpcat1 and Lpcat2 increased after infection." (PMID 40463366, 2025). "Furthermore, LPCAT1 aids membrane integrity, in part by helping to replace damaged lipids, including those that could induce ferroptosis that may be triggered by infection (86, –, 88)." (PMID 40827916, 2025).
liver (1 paper, 2021). "The LPCAT1-TERT fusion event initially detected in case ETT-1 was identified in a liver metastasis that was resected three years after initial diagnosis and treatment of ETT." (PMID 34033669, 2021).
metabolic disorders (1 paper, 2025). "GSPT1 was implicated in the development of metabolic disorders through its effects on the cell cycle and protein synthesis, while LPCAT1 influenced lung function and reproductive health by regulating the phospholipid composition of cell membranes." (PMID 40555906, 2025).
LPCAT1 also shares sentences with these, for which no sentence is quoted: adenocarcinoma (3 papers); ulcerative colitis (2); allergic disease (1); Barrett's oesophagus (1); brain glioma (1); colitis (1); coronary artery disease (1); diabetes (1); endometrial tumor (1); gestational trophoblastic neoplasm (1); Glucose intolerance (1); head and neck squamous cell carcinoma (1); Insulin resistance (1); Leber congenital amaurosis (1); lung diseases (1); neurodegenerative disease (1); neurological diseases (1); ovarian serous cystadenocarcinoma (1); peripheral nerve injury (1); pneumonia (1); prostate tumors (1); retinal disorder (1); skin cancer (1); squamous cell carcinoma (1); squamous cell carcinoma of the skin (1); T-cell lymphoma (1); triple-negative breast carcinoma (1).